CRP (C-reactive protein)
Diseases named in the same sentence as CRP in open-access papers (continued):
Sharing a sentence is not in itself a finding about the gene and the disease.
Stroke (continued). "The CRP level did not significantly differ between the stroke group and the non-stroke group." (PMID 34135849, 2021). "In our study, CRP at ICU admission was elevated mildly in the SAP group (12.9 vs. 5.3 mg/L, p < 0.001) compared to non-SAP, which might be a somatic response to acute stroke or correlate with stroke-induced immunodepression." (PMID 34925251, 2021). "Moreover, two independent studies demonstrated that administration of atorvastatin 80 mg/day did not affect the concentration of CRP in stroke patients." (PMID 34489618, 2021). "This assumption could be supported by the analysis of in-hospital data, which showed that patients who developed stroke in the early disease phase generally had a higher disease activity (BVAS) and inflammatory markers of erythrocyte sedimentation rate (ESR) and C-reactive protein (CRP)." (PMID 33868249, 2021). "The mechanisms by which statins reduce CRP levels in stroke patients are not precisely known." (PMID 34489618, 2021). "No relation was found between log(hs-CRP) and myocardial infarction or stroke." (PMID 34753497, 2021). "In the Justification for the Use of Statins in Prevention: an Intervention Trial Evaluating Rosuvastatin (JUPITER), lower rates of myocardial infarction, stroke and death were found following Rosuvastatin regimens in otherwise healthy adults with baseline CRP level ≥ 2mg/L and no hyperlipidemia." (PMID 34394107, 2021). "Identifying effective biomarkers for the early suspicion of acute stroke is clinically important; however, the role of CRP in stroke detection remains unknown owing to the lack of reports, especially those involving patients with dizziness." (PMID 34135849, 2021). "Second, our study did not include inflammatory indicators such as CRP and PCT, as well as risk factors for stroke‐related pneumonia, nutritional status, and oral function, which could have an impact on our conclusions." (PMID 33942561, 2021). "In the multivariate analysis, higher CRP level remained an independent predictor of depressive symptoms at day 8 (OR: 2.89, 95%CI: 1.47–5.69, P < 0.01), but not depressive symptoms assessed 3 months after stroke (OR: 1.21, 95%CI: 0.56–2.60, P = 0.62)." (PMID 31996746, 2020). "In the multivariate analysis, higher CRP level remained an independent predictor of depressive symptoms at day 8 (OR: 2.13, 95%CI: 1.18–3.82, P = 0.01), but not depressive symptoms assessed 3 months after stroke (OR: 1.53, 95%CI: 0.86–2.73, P = 0.14)." (PMID 31996746, 2020). "Therefore, CRP apheresis will not delay acute guideline therapies of stroke, such as intravenous lysis and intraarterial thrombectomy." (PMID 32932587, 2020). "Nevertheless, CRP apheresis fits well into the management of stroke patients because it does not collide with acute measures and may therefore complement methods aiming at reperfusion." (PMID 32932587, 2020). "Furthermore, the total cholesterol level (unstandardized coefficient β = -0.008, P = 0.001) and hs-CRP level (unstandardized coefficient β = -0.474, P = 0.012) were inversely correlated with the △LF/HF ratio in patients without stroke." (PMID 28302058, 2017). "Moreover, we found that hs-CRP level was inversely correlated with the △LF/HF ratio in patients without stroke." (PMID 28302058, 2017). "C-reactive protein (CRP) is a sensitive marker of chronic low-grade inflammation in community-dwelling adults and is associated in population-based studies with an increased risk of incident coronary heart disease (CHD), stroke, and non-vascular mortality." (PMID 27955697, 2016). "Notably, CRP levels provided no prognostic information for clinical outcome 90 days post stroke (data not shown)." (PMID 27152948, 2016). "The study demonstrated that eye acupuncture is a safe and effective treatment for stroke patients on symptoms alleviation and the dependency in the results of CSS, SSS, ADL, FMA, MMSE, HAMD, WST, and first defecation time as well as the biochemistries tests (CRP, ET, VEGF, and CGRP)." (PMID 26161127, 2015).
Stroke (continued). "Fourth, we did not measure inflammation and stress markers in stroke patients, only CRP." (PMID 24188156, 2013). "Prospective epidemiological studies have shown that serum levels of C-reactive protein (CRP), a biomarker of inflammation, are a strong predictor of cardiovascular ischaemia-reperfusion injury cycle events, such as myocardial infarction, postoperative atrial fibrillation and stroke." (PMID 23936799, 2013). "To determine the associations between AIS extent and YKL-40 and CRP levels in a homogenous etiologic (noncardiogenic) group, we analyzed YKL-40 and CRP levels in the context of 2 stroke subtypes (LAA and SVO) and found that the levels were dependent on AIS subtype and admission day." (PMID 23272150, 2012). "Since CRP was associated with stroke severity and the pre-existing DM, and the patient sample spanned a wide age range, we wanted to see if the effect of CRP on outcomes was independent of stroke severity, age, gender, effect of intravenous thrombolysis and presence of DM." (PMID 19400931, 2009). "We tested whether interleukin (IL)-6, C-reactive protein (CRP), and fibrinogen more strongly associate with fatal compared to nonfatal myocardial infarction (MI) and stroke." (PMID 19554082, 2009). "Importantly, negative or context‐dependent findings must shape use: hs‐CRP does not uniformly improve stroke prediction across populations, as shown in older community cohorts and in more recent analyses in which incremental discrimination gains were small and even inconsistent." (PMID 41567175, 2026). "However, given that almost half of the post-stroke patients experience moderate to severe functional impairment, using a biomarker such as CRP to predict recovery rather than mortality may present clinical value during rehabilitation." (PMID 36769677, 2023). "Although CRP and Pf1+2 have been associated with the presence and severity of WMH in the elderly, and hs-cTNT and fibrinogen with the presence of WMH in patients with acute ischemic stroke, little is known about their relation to WMH in the AF population without stroke." (PMID 34689250, 2022). "Moreover, the expression of RGM-A rather than other inflammatory indicators, such as CRP and IL-6, continued decreasing 8 to 14 days after stroke, indicating that SIDS might last longer than the inflammatory response." (PMID 36188375, 2022). "Pre-clinical studies show that selected serum biomarkers including C-reactive protein (CRP), interleukin-6 (IL-6), tumor necrosis factor-alpha (TNFα), matrix metallopeptidases (MMP), and vascular endothelial growth factors (VEGFs) may play a role in BBBP post-stroke." (PMID 34744972, 2021). "Finally, the lower level of s-IGF-II in cardioembolic stroke abided after stratifying for stroke severity and CRP (data not shown), as well as remaining significant after 3 months, which argues against the notion that this finding merely reflects an acute stress response." (PMID 34072372, 2021). "Notably, a Nigerian clinical study demonstrated that patients with moderate/severe motor disability at 30 days post-stroke had markedly higher levels of serum C-reactive protein (CRP), a non-specific biomarker of inflammation, when compared to those with mild disability." (PMID 34884906, 2021). "However, an elevated CRP level predicted future mortality independent of stroke severity." (PMID 30718369, 2019). "In accordance with the initial hypothesis, post-stroke temperature elevation seems to be associated with NIHSS status at admission as well as with gender, swallowing difficulties, intubation and CRP >50 or signs of infection at admission, but not with hemorrhage or ischemic stroke." (PMID 29237408, 2017). "Finally, inflammation assessed by increased CRP and interleukin-6 (IL-6) levels match OSAS severity and may further contribute to vascular meta-inflammation processes, early atherosclerosis, arterial stiffness, and endothelial dysfunction, ultimately favoring stroke onset." (PMID 40149635, 2025).
Stroke (continued). "The investigation did not identify any major shifts in CRP levels, the frequency of positive temporal biopsies, or clinical features comparing GCA patients with and without stroke at the time of GCA confirmation." (PMID 39817601, 2025). "A1AG1, CRP, and LBP were upregulated, while TTR, ApoC2, and RBP4 were downregulated in patients with stroke and AF, compared to patients with stroke without AF." (PMID 38886511, 2024). "Across the overall population, stroke volume had a weak negative correlation with serum urea, bilirubin, aspartate aminotransferase, ALP, γ‐glutamyl transferase, CRP, and troponin‐T, and a weak positive correlation with serum albumin." (PMID 38314569, 2024). "This is in good accordance with a previous survey comprising patients with stroke regardless of PFO, while cases with evidence for DVT had an increased CRP compared to those without." (PMID 39187799, 2024). "The decision tree analysis demonstrated a heightened probability of new-onset stroke among hypertensive individuals with a CVAI equal to or greater than 83, coupled with a C-reactive protein level no less than 1.1 mg/l." (PMID 37337187, 2023). "The decision tree analysis demonstrated a heightened probability of new-onset stroke among hypertensive individuals with a CVAI equal to or greater than 83, coupled with a CRP level no less than ≥ 1.1 mg/l." (PMID 37337187, 2023). "Instead, we observed a strong association of LV-MVR with 11 non-cardiac traits, including 5 stroke subtypes, VTE, CRP, and FEV1." (PMID 36778476, 2023). "COVID-19 infection increased the likelihood of death 3 months after stroke and reperfusion therapy seven times (OR 6.696; 95% CI 1.029–43.584), while hypoxemia, total WBC count, and CRP concentration were not significant predictors." (PMID 35683393, 2022). "Alternatively, it is possible that Gram-positive bacteria induce CRP via different molecules than LTA, and these molecules are not increased with stroke since there probably are no live Gram-positive bacteria in blood following most strokes." (PMID 33753837, 2021). "Associations of CRP and fibrinogen may not be consistent across subtypes of IS (e.g. large artery, small vessel, and cardio-embolic) and ICH (e.g. lobar and non-lobar), something that will be investigated once ongoing characterization of stroke subtypes in CKB is complete." (PMID 32221345, 2020). "Although other studies found a correlation between CRP, increased CCA-IMT, and stroke, our study found only a trend in this direction (not statistically significant)." (PMID 30987675, 2019). "The alterations in CRP and IFN-γ, were similar as above in stroke patients with and without infections." (PMID 27682880, 2017). "Stroke severity at admission based on the National Institutes of Health Stroke Scale (NIHSS), the degree of intracranial stenosis, C-reactive protein (CRP) and total cholesterol (TC) concentration were not significantly different between the two groups." (PMID 23251528, 2012). "Moreover, CRP levels were not predictive of functional outcome in a study of patients receiving thrombolysis in contrast to several studies involving exclusively or mainly conservatively treated patients, thereby further underscoring the influence of thrombolysis on inflammation after stroke." (PMID 21712986, 2011). "Regarding laboratory parameters, stroke patients with evidence of DVT, compared to those without, presented increased levels of D-dimer (p = 0.01), CRP (p = 0.038; OR 3.41, 95%-CI 1.25–9.81 for cut-off at 5 mg/L), and LA-specific aPTT (p = 0.032; OR 4.85, 95%-CI 1.89–17.06 for > 35 s)." (PMID 39187799, 2024). "Therefore, timely CRP monitoring is crucial for predicting potentially lethal CVD events, including heart attacks and strokes, which often occur with no symptoms or signs." (PMID 36551130, 2022).
Stroke (continued). "Growing antecedents reported in the literature indicate that elevated circulating inflammatory markers, such as C-reactive protein (CRP), predict coronary events, stroke, and progression of peripheral disease independent of the severity of atherosclerotic or ischemic events." (PMID 33841183, 2021). "Independent predictors of 90-day mortality were WBC < 6.4 × 109 /L (OR = 5.00, 95% CI: 1.49-16.78), baseline National Institute of Health Stroke Scale (NIHSS) score (OR = 1.13 per point, 95% CI: 1.01-1.25) and bleeding brain complications (OR = 5.53, 95% CI: 1.59-19.25) but not CRP ≥ 8.65 mg/L." (PMID 33920119, 2021). "Although other inflammatory biomarkers like high-sensitivity C-reactive protein (hs-CRP) and leukocytes have been reported to be useful in predicting clinical outcome after stroke, there has been no head-to-head study to date that compares these markers in terms of predictive value." (PMID 24895559, 2014). "Levels of MCP-1, CRP and TIMP-1 did not significantly differ between stroke patients and controls." (PMID 23158556, 2012). "Although CRP and ESR were elevated, these acute-phase proteins are not specific to etiology and may be elevated in response to tumor, stroke, and seizures as well as infection and inflammation." (PMID 22389820, 2011). "Our results suggest that CRP levels above 50 mg/L, body temperature above 38 °C or WBC above 11 × 10^9/L (or above 12 × 10^9/L the first 24 h after stroke) are highly unlikely to be an effect of stroke itself and should be suspected to be signs of a complication, most commonly a bacterial infection." (PMID 40447994, 2025). "Furthermore, with the exception of the CRP level (P < 0.05), the other inflammatory predictors (IL-6 level, NLR, WBC count, and NEUT%) did not change significantly within 24 h after stroke (P > 0.05)." (PMID 36188375, 2022). "We observed that clinically assessed disease activity of TAK (using ITAS2010, DEI.TAK, or NIH criteria), CRP, and neutrophil: lymphocyte ratio at presentation were similar at presentation in those TAK patients with stroke/TIA when compared with those without stroke/TIA." (PMID 36431038, 2022).
lymphopenia (1,119 papers, 2003 to 2026). Reduction in the number of lymphocytes. "Severe immunodeficiency (SID) was associated with fever, neurological symptoms, lymphopenia, and elevated C-reactive protein (CRP) (all P < 0.01)." (PMID 41485003, 2026). "PIICS is defined by the presence of lymphopenia, elevated CRP levels, and evidence of catabolism through weight loss or hypoalbuminemia in the context of a prolonged hospitalization." (PMID 42028952, 2026). "In our cohort, more advanced AKI stages were associated with marked lymphopenia and significantly higher levels of inflammatory and coagulation markers, including D-dimer, ferritin, CRP, procalcitonin, and IL-6." (PMID 41598421, 2026). "Accumulating evidence indicates that hyperglycemia is associated with profound immune dysfunction, including lymphopenia, elevated CRP and D-dimer, and coagulation abnormalities." (PMID 41156159, 2025). "These comorbidities, along with factors like advanced age, severe lymphopenia, elevated CRP, and D-dimer levels above 1 μg/L, are strongly associated with a poor prognosis and increased mortality rates." (PMID 40283596, 2025). "Beyond elevated CRP, lymphopenia is frequent in SLE and linked to high disease activity and renal involvement." (PMID 40988967, 2025). "Lymphopenia and elevated CRP are associated with increased severity in pediatric H1N1pdm09 infection (Severity/Prognosis)." (PMID 41583233, 2025). "Factors associated with difficulty in decannulation included lymphopenia, age ≥75 years, head and neck disease, and elevated CRP." (PMID 40786461, 2025). "Opacity scores were analyzed according to the covariates associated with greaterseverity, such as consolidation, lymphopenia, elevated C-reactive protein, andelevated LDH." (PMID 41523926, 2025). "Serial trends in viral antigen, CRP and IL-6, provide support that new or persistent lymphopenia is associated with ongoing viral replication and inflammation." (PMID 39810077, 2025). "The results found that lymphocytopenia, hypoalbuminemia, high CRP, and decreased LVEF were independently associated with the risk of severity among children with MIS-C." (PMID 38982132, 2024). "Our study also found that in infected patients, in addition to common lymphopenia, increases in leukocytes, neutrophils, CRP, AST and D-dimer were associated with severe disease and death outcomes (p < 0.05)." (PMID 38831260, 2024). "Specifically, the authors found that LDL-c ≤ 69 mg/dl, C-reactive protein > 88 mg/dl, and lymphopenia <1000 at admission were independently associated with 30-day mortality." (PMID 37936960, 2023). "In a large population of 31,178 outpatients, in addition to lymphopenia, high levels of C-reactive protein (CRP) were also associated with reduced survival." (PMID 38042792, 2023). "Laboratory parameters such as elevated C-reactive protein, ferritin, D-dimers, and lymphopenia were associated with severe disease." (PMID 37791149, 2023). "A report evaluated a series of cases and established that high LDH levels upon admission, advanced age, CRP, and lymphopenia were linked to the requirement for an intensive care unit (ICU)." (PMID 37754237, 2023). "Previous studies have proposed that lymphopenia and higher serum levels of CRP, D-dimers, ferritin, and lactate can be considered risk factors for severe COVID-1953." (PMID 37932287, 2023). "Advanced age, systemic inflammation (high CRP-levels), and lymphocytopenia were associated with a more severe clinical outcome (data not shown)." (PMID 35987708, 2022). "Respiratory distress, lymphopenia, thrombocytopenia, elevated CRP and hyperglycemia were significantly associated with an unfavorable outcome." (PMID 35729416, 2022). "Consistently, our study demonstrated that both men and women presented increased inflammation and coagulation, as suggested by the higher levels of CRP, ferritin, procalcitonin, NT proBNP and lymphopenia were at a higher risk of death." (PMID 36224551, 2022).